BATF3 (basic leucine zipper ATF-like transcription factor 3)
Description:
AP-1 family transcription factor that controls the differentiation of CD8(+) thymic conventional dendritic cells in the immune system. Required for development of CD8-alpha(+) classical dendritic cells (cDCs) and related CD103(+) dendritic cells that cross-present antigens to CD8 T-cells and produce interleukin-12 (IL12) in response to pathogens (By similarity). Acts via the formation of a heterodimer with JUN family proteins that recognizes and binds DNA sequence 5'-TGA[CG]TCA-3' and regulates expression of target genes.
Synonyms: SNFT; JUNDM1; JDP1
Tractability: PROTAC: ubiquitination databases record sites on it.
Gene: Protein-coding gene on chromosome 1 (212,686,417 to 212,699,840, reverse strand). Ensembl gene ENSG00000123685.
Subcellular location: Nucleus
Subcellular location (Human Protein Atlas): Nucleoli; Cytosol; Nucleoplasm
Gene Ontology:
Molecular function: DNA-binding transcription repressor activity, RNA polymerase II-specific; protein binding; RNA polymerase II cis-regulatory region sequence-specific DNA binding; sequence-specific double-stranded DNA binding; DNA-binding transcription factor activity; DNA-binding transcription factor activity, RNA polymerase II-specific; DNA binding
Biological process: negative regulation of transcription by RNA polymerase II; dendritic cell differentiation; integrated stress response signaling; myeloid dendritic cell differentiation; regulation of transcription by RNA polymerase II; response to virus; regulation of DNA-templated transcription
Cellular component: nucleolus; nucleoplasm; RNA polymerase II transcription regulator complex; chromatin; nucleus
Genetic constraint (gnomAD): Loss-of-function variants: 6 observed, 10.82 expected, observed/expected ratio (o/e) 0.55, 90% interval 0.3 to 1.09. The upper end of that interval is the gene's LOEUF score, 1.09, which puts it in group 4 of 6, group 1 being the genes least tolerant of losing a copy. Missense variants: 128 observed, 134.21 expected, observed/expected ratio (o/e) 0.95, 90% interval 0.82 to 1.1. Synonymous variants: 68 observed, 59.89 expected, observed/expected ratio (o/e) 1.14, 90% interval 0.93 to 1.39.
Homologues: Orthologues: chimpanzee BATF3 (96% identical), dog BATF3 (93% identical), pig BATF3 (89% identical), mouse Batf3 (80% identical), macaque BATF3 (79% identical), guinea pig BATF3 (73% identical), rat Batf3 (72% identical), tropical clawed frog BATF3 (63% identical), zebrafish batf3 (45% identical), Drosophila melanogaster Atf3 (35% identical). Paralogues in human: BATF (44% identical), BATF2 (35% identical), FOS (31% identical), FOSL2 (31% identical), JDP2 (31% identical), FOSB (30% identical), FOSL1 (29% identical), ATF3 (27% identical).
Diseases named in the same sentence as BATF3 in open-access papers:
BATF3 is named in the same sentence as 97 diseases in open-access papers, as found by Europe PMC text mining. Sharing a sentence is not in itself a finding about the gene and the disease. The quoted sentences say what the papers report.
melanoma (16 papers, 2014 to 2024). A malignant, usually aggressive tumor composed of atypical, neoplastic melanocytes. "In preclinical experiments, the major source of CXCL10 within melanomas appeared to be, again, Batf3-lineage DCs, suggesting the key role of these DCs in the anti-tumor T cell response." (PMID 38928238, 2024). "In a melanoma mouse model, Batf3+ DCs were a dominant source of CXCL9." (PMID 38928238, 2024). "Importantly, the expression of Batf3-dependent DC transcripts in human melanoma tumors correlates with CXCL9/10 expression and CD8 T cell infiltration, suggesting that Batf3-dependent cDC1s might regulate T cell recruitment to tumors in both mice and human." (PMID 30619378, 2018). "In a melanoma mouse model, the XCL1 and CCL5 produced by NK cells recruited Batf3 DCs to the tumor microenvironment." (PMID 38928238, 2024). "In Wnt/β-catenin-positive melanoma tumors, decreased production of chemokine CCL4 leads to reduced recruitment of BATF3 DCs to the TME." (PMID 34983532, 2022). "Consistent with previous studies, both B16-F1 melanoma cells and MC38 colon cancer cells grew faster in Batf3–/– mice." (PMID 34283809, 2021). "The presence of BATF3+ dendritic cells (DCs), which cross-present antigens from dying cancer cells to CD8+ T cells, is critical for immunotherapy efficacy in melanoma." (PMID 31287991, 2019). "We utilized the B16-SIY melanoma model, CD11c-DTR-GFP bone marrow chimeras and CD11c-DTR-GFP/Batf3 KO mixed bone marrow chimeras to study the role Batf3-DCs play during anti-PD-L1 immunotherapy." (PMID 30400822, 2018). "In melanoma cells in vivo, Wnt/β-catenin signaling prevents the priming of antitumor responses by disrupting the recruitment of dendritic cells expressing basic leucine zipper transcriptional factor ATF-like 3 (BATF3)." (PMID 39271499, 2024). "Furthermore, we compared tumor-infiltrating classic CD8a+ DCs population, synonymous with Batf3+ DCs, because this subset is a key orchestrator of immune responses in cancer and our previous work demonstrated that ptges depletion could enhance this population in melanoma." (PMID 37529399, 2023). "Tumors expressing β-catenin showed lack of recruitment of the Batf3-lineage DCs expressing the surface markers CD103 or CD8α as a result of insufficient production of the critical chemokine CCL4 by the melanoma cells." (PMID 30477280, 2018). "We compared WT (wildtype) with Rag1–/–, Batf3–/–, Clec9agfp/gfp, sGsn–/– or sGsn–/– Clec9agfp/gfp mice implanted with transplantable tumor cell lines, including MCA-205 fibrosarcoma, 5555 BrafV600E melanoma and B16-F10 LifeAct (LA)-ovalbumin (OVA)-mCherry melanoma." (PMID 36162919, 2022). "We observed in transplantable melanoma, glioma and metastatic breast carcinoma models that DCIL-15-based DNA vaccines in which DC specifically express IL-15 and simultaneously produce tumor Aghsp70 were able to mediate potent therapeutic efficacy that required both host Batf3+ DC and CD8+ T cells." (PMID 25941586, 2014). "A non-inflamed melanoma TME has been correlated with failed recruitment and activation of Batf3-lineage dendritic cells." (PMID 30477280, 2018).
lymphoma (11 papers, 2017 to 2024). A malignant (clonal) proliferation of B- lymphocytes or T- lymphocytes which involves the lymph nodes, bone marrow and/or extranodal sites. "BATF/BATF3 are important for expression of genes in ALK+ ALCL that are associated with the TH17/group 3 innate lymphoid cell gene signature observed in this lymphoma." (PMID 33413671, 2021). "Indeed, we recently showed that in HL and ALCL, MYC is a direct target of BATF3, so that the promotion of constitutive expression of this proto-oncogene is presumably a main pathogenic function of BATF3 in these lymphomas." (PMID 29662618, 2018). "Among lymphomas, HL and BL showed the most specific genes, with HL having unique TFs like BATF3 and ISX1." (PMID 39769352, 2024). "In particular, tumor cells of those lymphoma entities, whose diagnostic differentiation from cHL is sometimes difficult (ALCL, DLBCL, PMBL, THRLBL, PTCL and NLPHL) showed increased BATF3 expression." (PMID 34202976, 2021). "BATF3-expressing tumor cells were observed in 100 of the 218 lymphoma samples and were not limited to cHL." (PMID 34202976, 2021). "In this study, we performed immunohistochemistry and analyzed the BATF3 expression in lymphoma cells on 218 lymphoma samples belonging to 14 different lymphoma entities." (PMID 34202976, 2021). "We performed immunohistochemistry and analyzed the BATF3 protein expression in lymphoma cells on 218 lymphoma samples belonging to 14 different lymphoma entities." (PMID 34202976, 2021). "We observed BATF3-expressing tumor cells in 100 of the 218 (n = 100/218) lymphoma samples distributed across 11 of the 14 (n = 11/14) entities examined." (PMID 34202976, 2021). "Even so, by evaluating the BATF3 expression in analogy to the H-score method, we were able to demonstrate clear differences in the BATF3-scores between the individual lymphoma entities." (PMID 34202976, 2021). "As both of these are constitutively active in HRS cells of classical HL, in primary mediastinal B cell lymphoma, and ALCL, STAT and PI3K/AKT activities are main contributors of BATF3 expression in these lymphomas, as functionaly validated in HL cell lines." (PMID 29662618, 2018). "Apparently, the gene expression intensity influenced the development of the malignancies, as recipients of highly BATF3-transduced B cells succumbed earlier to lymphoma." (PMID 29662618, 2018). "Most intriguingly, the binding of JUN to BATF3 was also detectable in the cell lines of the BATF3-induced lymphomas." (PMID 29662618, 2018). "Further analyses revealed a germinal center B-cell-like phenotype of most BATF3-initiated lymphomas." (PMID 29662618, 2018). "BATF3 is involved in several cancers, such as colorectal cancer, glioma and lymphoma." (PMID 33714208, 2021). "BATF3-scoring was used to evaluate the BATF3 expression semi-quantitatively and to highlight the differences in the BATF3 expression between the individual lymphoma entities." (PMID 34202976, 2021). "Also, PRMT5 maintained the expression of the AP1 protein BATF3, which has been described as an upstream MYC-activator in Hodgkin lymphomas and T cell leukemia and is known to cause lymphomas of mature B cells in mice." (PMID 32555249, 2020). "As the B cells lacked BLIMP1 expression prior to transduction with BATF3-encoding retroviruses, it remains presently unclear whether a prevention of BLIMP1 upregulation is the main pathogenetic effect of BATF3 in this mouse lymphoma model." (PMID 29662618, 2018). "To unravel mechanisms involved in the lymphomagenesis of BATF3-triggered B-cell malignancies, we compared the expression of the AP-1 target gene BLIMP1 in freshly BATF3-transduced murine B cells and three B-cell lines established from our BATF3-induced lymphomas." (PMID 29662618, 2018).
lymphoma (continued). "To assess the oncogenic potential of BATF3 in lymphomagenesis and to dissect the molecular interactions of BATF3 in lymphoma cells, we retrovirally transduced murine mature T and B cells with a BATF3-encoding viral vector and transplanted each population into Rag1-deficient recipients." (PMID 29662618, 2018). "To test this hypothesis, we performed co-immunoprecipitation (Co-IP) experiments with the BATF3-induced lymphoma cell lines." (PMID 29662618, 2018). "Moreover, Western blot analysis revealed high expression of BATF3 in the lymphomas, with a considerable variation between cases." (PMID 29662618, 2018). "We did not detect any genetic alterations in the coding sequence of BATF3 in the human lymphomas that might explain the strong BATF3 expression." (PMID 29662618, 2018). "HBZ binds to an ATLL-specific BATF3 SE and controls the expression of BATF3 and its downstream targets, including MYC, thereby promoting the proliferation of lymphoma cells." (PMID 37501079, 2023). "The elevated expression of several AP-1 proteins including c-Jun, JunB, ATF3, BATF, and BATF3 has also been described in CD30-positive lymphomas." (PMID 33413671, 2021). "We are the first to report on the BATF3 expression status in ITCL, PCN and MZL, but some of the lymphoma entities in this study included only a few samples." (PMID 34202976, 2021). "In particular, BATF3 can dimerize with Jun in the MYC promoter and support the proliferation and survival of lymphoma cells." (PMID 29661228, 2018). "They show that prototypical CD30+ lymphomas, namely cHL (21/30) and mDLBCL (8/9), but also CD30+ DLBCL (15/20) frequently express BATF3 protein." (PMID 29057015, 2017). "They conclude that in cHL and ALCL STAT-mediated BATF3 expression is essential for lymphoma cell survival and promotes MYC activity, indicating a new oncogenic axis in these lymphomas." (PMID 29057015, 2017). "STAT-mediated BATF3 expression is crucial for lymphoma cell survival and promotes MYC activity in classical Hodgkin lymphoma and anaplastic large cell lymphoma, and a new oncogenic axis is recognized in these lymphomas." (PMID 30987332, 2019). "We challenged both wild-type and Batf3−/− mice with GFP+ luciferase-expressing A20 lymphoma cells (A20.GL) and, as expected, no CD11b−CD103+ cDC1 cells were present in the tumor of Batf3−/− mice." (PMID 33268774, 2020).
anaplastic large cell lymphoma (10 papers, 2017 to 2025). Anaplastic large cell lymphoma (ALCL) is a rare and aggressive peripheral T-cell non-Hodgkin lymphoma, belonging to the group of CD30-positive lymphoproliferative disorders, which affects lymph nodes and extranodal sites. "BATF3 has been previously implicated in Anaplastic Large Cell Lymphoma as being overexpressed and essential to tumor growth." (PMID 41000815, 2025). "A factor repressed upon PRMT5 inhibition, is the Basic Leucine Zipper ATF-like Transcription Factor, BATF3, which was shown to be required for proliferation in Hodgkin lymphoma, anaplastic large cell lymphoma as well as adult T cell leukemia/ lymphoma." (PMID 32555249, 2020). "In another study, BATF3 was found to be highly upregulated in the T-cell malignancy anaplastic large cell lymphoma (ALCL)." (PMID 29662618, 2018). "BATF3 expression has been previously demonstrated to regulate the expression of IL-2Rα/β in anaplastic large cell lymphoma, and indeed we found that IL2Ra was significantly upregulated in pomalidomide-treated HIV-specific CD8+ T-cells (3.25-fold, FDR = 3.94E-11)." (PMID 41232235, 2025). "BATF3 has been reported to induce MYC activity and thereby promote tumor growth in anaplastic large cell lymphoma, consistent with the MYC targets molecular program enriched in cALCL." (PMID 37790936, 2023). "In addition, BATF3 drives Th17-skewing phenotype in anaplastic large cell lymphoma (ALCL), and TCF7 confers progenitor exhausted T cell state." (PMID 37790936, 2023). "We observed varying degrees of BATF3 expression in nearly half of the cases (n = 100) with BATF3 expression being a constitutive feature of cHL (n = 53) and anaplastic large cell lymphoma (ALCL)." (PMID 34202976, 2021). "Recently, it has been reported that BATF3 forms AP-1 complexes with JUN in the MYC promoter and controls MYC expression in cHL (classical Hodgkin lymphoma) and ALCL (anaplastic large cell lymphoma) cell lines, critically supporting their proliferation and survival." (PMID 29661228, 2018).
glioma (8 papers, 2014 to 2022). A benign or malignant brain and spinal cord tumor that arises from glial cells (astrocytes, oligodendrocytes, ependymal cells). "For example, circ-0014359 targeted miR-153 to regulate the PI3 signaling pathway to promote glioma development and circ_0034642 contributed to glioma cell proliferation by elevating the BATF3 expression through serving as a miR-1205 inhibitor." (PMID 34057019, 2021). "In gliomas, miR-1205 targets BATF3 to restrain cell growth and invasion." (PMID 35674190, 2022). "circ_0034642 was found to be overexpressed in glioma, which could sponge miR-1205 to accelerate glioma proliferation and metastasis by regulating BATF3." (PMID 34150336, 2021). "In addition, gliomas in the high-risk group had an elevated expression of genes involved in APC activation and function, including activated DC, MHC-I class, and Batf3-DC signature, which represent cross-presentation of antigen." (PMID 33796538, 2021).
breast carcinoma (7 papers, 2019 to 2024). "For example, CRISPRa and CRISPRi screening of CCR7 expression revealed that Basic Leucine Zipper ATF-Like Transcription Factor 3 (BATF3) overexpression boosts specific TMEM traits, enhancing HER2+ CAR-T efficacy against breast cancer." (PMID 39538305, 2024). "Our analysis revealed a positive correlation between CSF-2 (GM-CSF) and IRF8, BATF3, or CCR7 in both lung and breast cancer patient cohorts." (PMID 32759497, 2020). "Strikingly, CAR T cells co-expressing BATF3 markedly enhanced tumor control at two subcurative doses (2.5 × 105 and 5 × 105 CAR+ cells) compared to control CAR T cells in an orthotopic human HER2+ breast cancer model." (PMID 37945901, 2023). "In mouse models lacking BATF3+ DCs, IL-12 production and natural killer (NK) cell mediated control of metastasis is impaired while BATF3 and IRF8 expression have been associated with improved relapse-free survival in breast cancer patients." (PMID 31921140, 2019). "Consequently, CD8+ T-cell effector (Teff) score, comprising gene expression of IFNG, PRF1, CD8A and CD8B, and BATF3-DC score, calculated with the expression level of BATF3, IRF8, THBD, CLEC9A, and XCR118 were markedly increased in the high SLAMF6 group than in the low SL AMF6 group in breast cancer." (PMID 38287061, 2024).